IFNG (interferon gamma)
Diseases named in the same sentence as IFNG in open-access papers (continued):
Sharing a sentence is not in itself a finding about the gene and the disease.
bacterial infection (continued). "Significant reduction in serum interferon gamma (IFN-γ) release, elicited by bacterial infection, was also observed in BCP1-BGL-treated animals." (PMID 33500725, 2021). "Interferon gamma (IFN-γ) is a cytokine that plays a critical role in both innate and adaptive immunity against viral and bacterial infections." (PMID 31311960, 2019). "Interferon gamma (IFN-γ), a leading proinflammatory cytokine against viral and bacterial infections, is a representative source for MSC priming for functional enhancement." (PMID 31387282, 2019). "In brief, in this study, we found that the Runx3-IL12-STAT4 pathway can modulate the secretion of IFNγ by group 1 ILCs and NCR+ILC3s after intracellular bacterial infection." (PMID 30258450, 2018). "In particular, neutrophils are prominent in cellular infiltrates and increased pro-inflammatory cytokines (e.g. IL-8, TNFα, IFNγ and MCP-1) are a feature of acute exacerbations in asthmatic patients following viral and bacterial infections." (PMID 27657907, 2016). "Further, we identify GM-CSF/IFNγ-producing Th17 cells in EAE and persistent extracellular bacterial infection as bearing a CCR6−CCR2+ phenotype in mice and in humans." (PMID 26511769, 2015). "The LPS activated immune response to bacterial infection results in the production of NKT cells and IFNγ." (PMID 26121276, 2015). "This switch defines a unique in vivo cell surface signature (CCR6−CCR2+) of GM-CSF/IFNγ-producing Th17 cells in EAE and experimental persistent extracellular bacterial infection, and in humans." (PMID 26511769, 2015). "Indeed, various stimuli such as interferon-gamma (IFN-γ), IL-1β, TNF-α, and parasitic/bacterial infections induce iNOS expression in macrophages." (PMID 38456097, 2024). "The activation of surface α-enolase trigger the production of inflammatory factors (TNFα, IL1β, IFNγ and PGE2) and could be detrimental for the pathology but could be beneficial during bacterial infection." (PMID 35154105, 2022). "The main result was that IFNα1 and IFNγ, at their optimal doses, induced expression of CD169 on monocytes and of CD64 on neutrophils, respectively, at levels similar to what happens physiologically during the course of natural viral or bacterial infections." (PMID 32031762, 2020). "M1 polarization occurs via stimulation with several pro-inflammatory signals (e.g., LPS and IFNγ, with ensuing TNFα, and IL-6 production), as are normally elicited early after bacterial infection of the urinary tract." (PMID 32849562, 2020). "To examine more closely the role of Sts in regulating the IFNγ‐NO pathway, we stimulated cells with IFNγ in the absence of bacterial infection." (PMID 32841534, 2020). "Importantly, Th17 populations generated in response to persistent bacterial infection displayed similar cytokine-secreting repertoires as observed in EAE, as GM-CSF+ or IFNγ+ Th17 cells were found almost exclusively in the CCR6−CCR2+ population." (PMID 26511769, 2015). "Hence, IFNγ alone is most likely not able to control bacterial infection in vivo in the absence of NOS2." (PMID 32408806, 2020). "Although IFNγ production may be maintained in ESRD patients through IL-12/IL-18 stimulation of MAIT cells, the lower levels of TNFα production in response to microbial stimulation point to defects in the response to bacterial infection." (PMID 29868028, 2018). "However, the effect of pathogen-driven mitophagy on the initiation of specific pro-inflammatory programs, such as the interferon γ (IFNγ) response, and subsequent effect on neighbouring cells is not well known, nor abundantly studied, in the context of bacterial infections." (PMID 37410705, 2023). "Considering that IFNγ is known to play a protective role during several bacterial infections, including B. pseudomallei, these results suggested that the reduced resistance of Il-18-/- mice to B. pseudomallei infection may be due to lack of IFNγ induction." (PMID 22241982, 2011).
infectious disease (136 papers, 2006 to 2026). A disorder directly resulting from the presence and activity of a microbial, viral, or parasitic agent in humans. "The increased production of IFNγ by multicytokine-producing cells has been linked to better protection against various infectious diseases." (PMID 25328681, 2014). "These polymorphisms are often correlated with varying IFNG expression levels, where increased or decreased expression levels have been tied both to infectious disease risk and severity." (PMID 25479081, 2014). "The association of IFNG +874 T/A with several other infectious diseases has been studied so far." (PMID 29531550, 2017). "In conclusion, we identified genes that act directly within the GR signal transduction pathway as well as GR-associated genes including TNF and IFNG that have both been associated with prenatal iAs or Cd exposure in humans and established to play a role in infectious disease." (PMID 25479081, 2014). "Susceptibility to infectious diseases is influenced by the genetic background and it is supposed that efficient activation of cellular immune response specifically the IFNG/IL-12/23 axis might play a key role in protection." (PMID 17456233, 2007). "On the other hand, the protective role of IFNγ-producing B cells by promoting Th1 cells in infectious diseases has been well documented." (PMID 37759658, 2023). "IFNγ is thought to shift hematopoiesis in favor of monocytes during inflammation based on models of infectious disease in mice." (PMID 35522671, 2022). "are frequently used as folk medicinal plants in Taiwan for the treatment of different infectious diseases, and both were found to induce the secretion of interferon-gamma (IFN-γ) and lymphocyte proliferation at low concentrations." (PMID 34202844, 2021). "The role of NK cells is actively studied at the present time and according to the literature, the main function of NK cells in various models of infectious diseases is the contact cytolysis, as well as the synthesis of IFNγ." (PMID 31057785, 2019). "Interferon gamma, an important regulator of immune responses that mainly produced by multiple types of immune cells, plays an essential role in immuno-modulation in infectious diseases." (PMID 29563896, 2018). "Serpine1 also acts as an inflammatory mediator by increasing the level of interferon gamma in blood to eliminate the pathogen in the early phase of an infectious disease." (PMID 28542507, 2017). "Given the ties between iAs/Cd exposure, IFNG, and infectious disease, it is plausible that it represents a key player related to the GR pathway that underlies iAs/Cd exposure and disease susceptibility." (PMID 25479081, 2014). "It will be important to gain a better understanding of how IFNγ mediates the activation of dormant HSCs, how IFNγ signaling is regulated in these cells, and how this process impacts host defense during infectious diseases of public health significance." (PMID 22194881, 2011). "In addition, macrophages respond to multiple activators such as LPS, TNFα, and IFNγ in infectious diseases." (PMID 37569508, 2023). "Interestingly, TVM cells produce large amount of IFNγ in response to IL-12+IL-18 as previously demonstrated in infectious disease murine models." (PMID 36330506, 2022). "Interferon gamma is critically involved in immunomodulation in infectious diseases." (PMID 28936213, 2017). "One method for assessing the T‐cell's response to SARS‐CoV‐2 is the interferon‐gamma (IFN‐γ) release assay (IGRA), which is a blood‐based test for diagnosing infectious diseases by measuring the IFN‐γ secreted by antigen‐specific T‐helper cells (Th cells) in blood samples." (PMID 37032413, 2023). "We also observed significantly high expression levels of IFNγ, IL12, IL8, and COX2 in the TZO population suggesting they may play a role in chronic stress, infectious diseases, and autoimmune pathologies." (PMID 32116734, 2019).
inflammation (134 papers, 2009 to 2026). Aberrant reaction of the microcirculation characterized by movement of fluid and leukocytes from the blood into extravascular tissues. "The increased amount of pro-inflammatory cytokines such as interleukin-1B (IL-1B), interleukin-6 (IL-6), interleukin-12 (IL-12) and interferon gamma (IFN-γ) in the serum was shown to be associated with pulmonary inflammation and extensive lung damage in SARS patients." (PMID 34834033, 2021). "Notably, sensitization of IL-10-deficient mice with OVA/Alum/CpG resulted in the development of neutrophilic lung inflammation associated with IFNγ production." (PMID 28220116, 2017). "Notably, in IL-10-deficient animals, OVA sensitization with Alum/CpG-adjuvant resulted in the development of neutrophilic airway inflammation associated with IFNγ production, while in IL-10/IL-12p40 double-knockout (KO) mice it was associated with IL-17 production." (PMID 28220116, 2017). "Similarly, a recent study using CpG treatment in a chronic mouse lung inflammation model, demonstrated that the treatment-induced amelioration of disease was less dependent on the induction of IFNγ expression but was more associated with an enhanced regulatory T-cell response." (PMID 25901733, 2015). "Interleukin-5 (IL-5) contributes to eosinophil activation, while interleukin-17 (IL-17) and interferon-gamma (IFN-γ) from T-helper 1 (Th1) and T-helper 17 (Th17) cells drive chronic inflammation and further damage to the skin." (PMID 40161158, 2025). "These T cells also secrete pro-inflammatory cytokines such as IL-6, TNF-α, and interferon-gamma (IFN-γ), which exacerbate renal inflammation and injury." (PMID 40806733, 2025). "GO terms and the KEGG database indicated that pathways enriched in these two clusters were immune response, response to interferon-gamma (IFN-γ), antigen processing and presentation, and inflammation-related diseases." (PMID 38022502, 2023). "Previous studies have shown that FXR expression was significantly decreased after LPS stimulation in monocytes and IFNγ stimulation in macrophages, which indicated a link between chronic autoimmune inflammation and FXR expression." (PMID 33821438, 2021). "These pathological features are reproduced in a model of chronic meningeal inflammation generated by the injection of lentiviral vectors for the lymphotoxin-α (LTα) and interferon-γ (IFNγ) genes." (PMID 33315860, 2020). "Safranal has demonstrated anti-inflammatory effects on OVA-induced airway inflammation via modulation of type 1 and 2 helper T lymphocytes balance, evident from the reduced serum IL-4 and elevated IFNγ." (PMID 33324206, 2020). "A decrease in the abundance of CD11c+ cells in the airways is typically seen in airway inflammation, induced for example with lipopolysaccharide, antigen, recombinant IL-13 or Interferon gamma." (PMID 22110701, 2011). "Besides, both have been successfully implemented in the study of lung inflammation, showing cytokine responses upon proinflammatory triggers such as lipopolysaccharide (LPS), interferon gamma (IFN-γ) or tumor necrosis factor alpha (TNF-α)." (PMID 35832493, 2022). "Progression of HF was correlated with the accumulation of M1 macrophage phenotype in the myocardium and increased production of M1 macrophages, associated with production of proinflammatory cytokines such as IFNγ, IL-6, and TNFα, which all lead to cardiac inflammation." (PMID 30024944, 2018). "In rat models of systemic inflammation, a GLP-1 RA, exendin, significantly lowered pro-inflammatory cytokine levels, including IL-1β, IL-6, TNF-α, and interferon-gamma (IFN-γ)." (PMID 40735319, 2025). "However, since pY-STAT3 regulates inflammatory responses, both by blocking IFNγ induced STAT1 and IL-6 induced NFκB, inhibiting pYSTAT3 exacerbated cardiac inflammation." (PMID 36844399, 2023).
inflammation (continued). "In WT mice, intranasal OVA challenge does not results in lung inflammation while in IL-10 KO or IL-10/IL-12-KO mice intranasal OVA challenge induces airway neutrophilic inflammation and lung inflammation associated with IFNγ or IL-17 production." (PMID 28220116, 2017). "Recent data have suggested interferon-gamma (IFN-γ) and/or interleukin-2 (IL-2) to be protective rather than pro-inflammatory cytokines that could be involved in the down-regulation of RA-related chronic inflammation." (PMID 24221190, 2014). "Thus, the lack of efficacy of cis-UCA in the IL-10−/− mouse suggests the possibility that IL-10 secreting T-regulatory cells or γδ+ T cells may be critical for cis-UCA effects, and further, that the increased levels of IFNγ are not the primary driver of gut inflammation in this model." (PMID 21060867, 2010).
neurological diseases (42 papers, 2009 to 2025). "Since the pro-inflammatory cytokine IFNγ plays a key role in the pathology of several ERVK-associated neurological diseases, we sought to determine if IFNγ can drive ERVK RT expression." (PMID 25609305, 2015). "There are contradictory results regarding the roles of IFNγ in the pathogenesis of neurological disorders." (PMID 38482922, 2024). "The T cell response to SINV infection is paradoxical: T cell sourced IFNγ promotes viral clearance, but the onset of neurologic disease and inflammation is concurrent with the arrival of T cells into the CNS." (PMID 38695564, 2024). "The ratio of serum concentrations of Th1: Th2 cytokines, represented by IFNγ:IL-10, increased sequentially with disease duration in PD and was higher than of other neurological disorders and healthy controls." (PMID 30954070, 2019). "A significant increase in IFNγ levels with the increase in PD duration (3–12 years of PD) was evident compared to individuals with other neurological disorders (P < 0.001)." (PMID 30954070, 2019). "In contrast to the extensively described up-regulation of IFNγ in animal models of human central nervous system diseases, there is only very limited information about amounts of IFNγ in human individuals suffering from neurological diseases." (PMID 23162429, 2012). "Interferon gamma (IFNγ) is a main pro-inflammatory cytokine and up-regulated during several neurological diseases." (PMID 21371330, 2011). "We hypothesize that inhibiting the impact of IFNγ on NSPCs during neurological diseases might contribute to effective neurogenesis and regeneration." (PMID 21371330, 2011). "IFNγ is a key inflammatory cytokine, mainly produced by cytotoxic CD8+ T-cells and natural killer cells in the course of neurological diseases like cerebral traumata, stroke or multiple sclerosis." (PMID 21371330, 2011). "The correlation of IFNγ expression in SLEV-infected brains and the onset of severe neurological disease and mortality indicate that IFNγ could be involved in the pathogenesis of experimental St." (PMID 28330482, 2017). "Furthermore, ZIKV-infected patients showing neurological complications had higher expressions levels of IFNγ and IP-10, as compared to infected patients without neurological disease." (PMID 33378361, 2020).
cardiovascular disease (41 papers, 2008 to 2026). "Additionally, there was a significantly higher upregulation of genes associated with cardiovascular diseases (p = 0.0024) and the immune system (p = 0.0001) in the high compared to the low IFNG group." (PMID 38892346, 2024). "Long-term shiftwork negatively affects IFNγ (interferon gamma) The association of shiftwork-affected immune system with sleep deprivation increases inflammatory markers thereby causing malignancies and metabolic and cardiovascular disorders." (PMID 29607311, 2018). "This is in line with several experimental studies that show the proatherogenic role of both IL12 and IFNγ in cardiovascular disease." (PMID 32981416, 2020). "However, it should be noted that dysregulation of the TNF, IFNG, and TGFB seems more specific for classical cardiovascular disease." (PMID 38389898, 2024).
hematological malignancies (40 papers, 2012 to 2026). "In a recent study highlighting the possible detrimental effects of IFNγ in hematologic disorders, it was shown that IFNγ is not essential for CAR-T therapy." (PMID 38418901, 2024). "Platelet-derived RANKL then impairs NK antitumor reactivity with a more pronounced effect on IFNγ production as compared to cytotoxicity, which is again in line with observations on the differential effect of RANK/RANKL interaction on NK reactivity in hematological malignancies." (PMID 30813611, 2019).
kidney (40 papers, 2008 to 2025). "Upon analysis, expression of the cytokines IFNB1, IFNG (IFN-γ), TNF (TNF-α), TGFB1 (TGF-β), IL1B, IL2, IL6, CXCL8 (IL-8), and IL10 were all significantly increased in ‘mesenchymal’ lung ADC compared to ‘epithelial’ tumors." (PMID 29440769, 2018). "Moreover, this combined treatment reduces liver GVHD compared to PTCy alone, an effect that corresponds with an increase in human CD39+ Tregs and a decrease in human serum IFNγ." (PMID 38339054, 2024).